ATG14 (autophagy related 14)
Diseases named in the same sentence as ATG14 in open-access papers (continued):
Sharing a sentence is not in itself a finding about the gene and the disease.
cancer (7 papers, 2019 to 2025). A tumor composed of atypical neoplastic, often pleomorphic cells that invade other tissues. "Accordingly, Vps34- or Atg14-dependent gene signatures were elevated in intratumoral Tregs from human cancer patients." (PMID 40215232, 2025). "In both the control and cancer patients, there were positive correlations (p < 0.0001) between KRAS mutational status and the expression of MAP1LC3B, ATG5, ATG10, ATG13, and ATG14." (PMID 39057088, 2024). "We reconfirmed the correlational analysis data with the expression of MAP1LC3B, ATG5, ATG13, and ATG14 in cancer patients, in KRAS-mut compared to KRAS-WT (p < 0.05)." (PMID 39057088, 2024). "By analysis of The Cancer Genome Atlas database, the mRNA level of USP1 was positively correlated with ATG14, UVRAG, and PIK3C3 (VPS34)." (PMID 39814232, 2025). "KAT5/TIP60-driven lactylation of PIK3C3/VPS34 at lysine residues 356 and 781 enhances its interaction with BECN1, ATG14, and UVRAG, promoting autophagy that may contribute to cancer progression." (PMID 39979245, 2025). "Indeed, among these targets, transcription of MAP1LC3B and ATG14 genes are directly controlled by this CARM1/TFEB during starvation, a process that could be also involved in cancers when cancer cells are frequently deprived." (PMID 31861179, 2019).
ATG14 also shares sentences with these, for which no sentence is quoted: Legionella infection (2 papers); liver fibrosis (2); metabolic disease (2); bacterial infection (1); chronic lymphocytic leukemia (1); Crohn disease (1); Diabetic Nephropathy (1); Dyskinesia (1); irritable bowel syndrome (1); ischemia (1); lung adenocarcinoma (1); myocardial ischemia (1); neuropathy (1); Obesity (1); Premature ovarian insufficiency (1); protein folding disorders (1); rectum adenocarcinoma (1); renal fibrosis (1); rheumatoid arthritis (1); type 2 diabetes (1).